SPARC (secreted protein acidic and cysteine rich)
Diseases named in the same sentence as SPARC in open-access papers (continued):
Sharing a sentence is not in itself a finding about the gene and the disease.
head and neck cancer (11 papers, 2016 to 2025). A primary or metastatic malignant neoplasm affecting the head and neck. "SPARC expression is also associated with tumor metastasis and poor prognosis in head and neck cancers." (PMID 37509139, 2023). "SPARC overexpression has been associated with a reduced disease-free interval and poorer OS in patients with head and neck cancer." (PMID 27411683, 2016). "This suggests that SPARC was associated with malignant phenotypes in head and neck cancer cells." (PMID 28718842, 2017). "Thus, the present study suggests that both exogenous SPARC and tumor-expressing SPARC might be associated with head and neck cancers." (PMID 28718842, 2017). "Therefore, based on the results of cDNA array and previous reports, SPARC is considered as a risk factor and might serve as a poor prognostic marker of head and neck cancer." (PMID 28718842, 2017). "YEATS2 regulates expression of epithelial-to-mesenchymal transition (EMT)-related SPARC in head and neck cancer (HNC)." (PMID 40810390, 2025). "BNCT was clinically approved for head and neck cancers; it is well known that many head and neck cancers overexpress SPARC and transferrin receptors." (PMID 37299673, 2023). "SPARC-related-signaling pathways and the role of exogenous and tumor-expressing SPARC have not been fully understood in head and neck cancers." (PMID 28718842, 2017). "In the present study, SPARC-induced phenotypes and signaling pathways in head and neck cancer cell lines were investigated and the expression of SPARC was examined in clinical tumor samples." (PMID 28718842, 2017). "Exogenous SPARC and SPARC overexpression enhances the EMT signaling pathway via AKT activation and may be associated with tumor progression in head and neck cancers." (PMID 37509139, 2023). "SPARC can enhance the proliferation and relocation of head and neck cancer cells." (PMID 37577749, 2023). "In head and neck cancer, the SPARC-induced effect and signaling pathways tends to a oncogenic role." (PMID 28718842, 2017). "Currently, the SPARC-induced signaling pathways and -associated kinases are not well known in head and neck cancer." (PMID 28718842, 2017). "However, the SPARC-induced signaling pathway was not fully understood in head and neck cancer." (PMID 28718842, 2017). "Our results suggest that SPARC treatment enhances the EMT signaling pathway via activation of AKT, and exogenous SPARC and tumor expressing SPARC might be associated with tumor progression in head and neck cancers." (PMID 28718842, 2017). "For example, inhibition of miR-29a can restore SPARC expression and enhance ECM production, while miR-203 suppresses SPARC-driven metastasis in head and neck cancers." (PMID 41018070, 2025). "In patients with head and neck cancer, NAB-paclitaxel drug remarkably reduced tumor size in SPARC-positive patients compared with that of the SPARC-negative group." (PMID 38347494, 2024). "For example, SPARC was reported to affect tumor cell proliferation and migration by activating PI3K/AKT signaling and the epithelial–mesenchymal transition in liver, lung, and head and neck cancers." (PMID 34348730, 2021).
liver cancer (11 papers, 2017 to 2025). An epithelial or non-epithelial malignant neoplasm that arises from the liver. "Studies indicated that SPARC participates in the glycolysis process of liver cancer cells by down-regulating the expression of HK2." (PMID 38076208, 2023). "Taken together, these results demonstrated a promoted effect of high SPARC expression on liver cancer growth." (PMID 34912848, 2021). "CCK8 and murine xenograft models were used to investigate the effect of SPARC on the liver cancer growth in vitro and in vivo." (PMID 34912848, 2021). "By using nude xenografted models, we found that SPARC overexpression promoted liver cancer growth." (PMID 34912848, 2021). "And moreover, the previous study showed that microRNA-211 could suppress liver cancer cell proliferation and invasion by targeting SPARC, which indicated that SPARC overexpression might drive progression of LIHC." (PMID 34912848, 2021). "Our research has provided a glimpse on the biological mechanism of SPARC and might contribute to the eventual treatment of liver cancer." (PMID 32670867, 2020). "However, it is necessary to further study the molecular mechanisms of the SPARC-related pathways in liver cancer." (PMID 32670867, 2020). "Furthermore, our experiments showed a promoted effect of endogenous SPARC overexpression on liver cancer cell proliferation in vitro and tumor growth in vivo, which might be associated with an increased cell ratio in S and G2 phases." (PMID 34912848, 2021). "TOP2A, CENPF, ACSL4, SPARC, and COL4A5 were significantly upregulated in patients with liver cancer, while they were downregulated by CTD treatment in HCC cells." (PMID 38017425, 2023). "In this study, we first analyzed the difference of SPARC expression between LIHC and normal controls, and then investigated the effects of SPARC overexpression on liver cancer cell proliferation in vitro and in vivo." (PMID 34912848, 2021). "Recent studies showed that, in liver cancer, overexpression of SPARC/BM-40 in HCC cells induced MET and resulted in reduced tumorigenesis." (PMID 31598149, 2019). "In the comparison between the liver cancer and the other cancer groups, cDMCs (FDR < 0.0001) were detected at the promoters of the SPARC, NEUROG1, SH3GL3, and ITGA4 genes." (PMID 28751909, 2017).
liver fibrosis (11 papers, 2011 to 2025). "Overall our data suggest that the liver of SPARC deficient animals have a gene expression profile which likely makes them less susceptible to develop liver fibrosis." (PMID 23408952, 2013). "Overall our results support the concept of basal conditions in the context of SPARC deficiency making the liver less susceptible to external insults such as those causing liver fibrosis." (PMID 23408952, 2013). "In murine fibrosis models, knockdown or knockout of SPARC markedly attenuates hepatic fibrosis, partly by suppressing the trans-differentiation of hepatic stellate cells (HSCs) into a myofibroblasts-like phenotype and inhibiting myofibroblasts activation." (PMID 40243151, 2025). "Liver fibrosis progression involves hepatic stellate cells (HSCs) that produce a secreted protein that is acidic and rich in cysteine (SPARC), a specific protein-binding protein that binds strongly to albumin." (PMID 33810483, 2021). "SPARC expression in hepatic tissue was significantly increased during the development of liver fibrosis, and targeting SPARC through an adenovirus carrying antisense SPARC suppressed HSCs activation in thioacetamide induced liver fibrosis in rats." (PMID 32933544, 2020). "We have previously demonstrated that SPARC−/− mice showed a reduced degree of liver fibrosis after 10 weeks of thioacetamide administration." (PMID 31289615, 2019). "Little information is available on the role of SPARC in human liver fibrosis, although we and others have shown that SPARC is overexpressed in the liver of cirrhotic patients." (PMID 29335425, 2018). "An earlier report has shown that knockdown of hepatic SPARC expression improves thioacetamide-induced liver fibrosis in rats with chronic liver injury." (PMID 26110898, 2015). "Expression of SPARC is increased in hepatic fibrosis due to activation of TGF-β1, a profibrotic cytokine with anti-inflammatory and immunosuppressive properties." (PMID 26110898, 2015). "Little information is available on the role of SPARC in human liver fibrosis: we (herein) and others showed that SPARC is overexpressed in the liver of cirrhotic patients." (PMID 23408952, 2013). "Liver fibrosis development was found markedly attenuated in SPARC−/− when compared to SPARC+/+ mice." (PMID 23408952, 2013). "In summary, we herein show that SPARC depletion in a mouse genetic model results in protection against liver fibrosis development." (PMID 23408952, 2013). "Interventions to inhibit SPARC expression are suggested as promising approaches for liver fibrosis treatment." (PMID 23408952, 2013). "Our data suggest that SPARC plays a major role in the pathogenesis of liver fibrosis, through myofibroblast recruitment/activation and induction of TGF-β1 expression." (PMID 23408952, 2013). "With this aim, two types of liver fibrosis in vivo models were applied to SPARC−/− and in SPARC+/+ mice: chronic TAA application and bile duct ligation." (PMID 23408952, 2013). "Expression of the SPARC gene is up-regulated in fibrotic liver while its down regulation by adenoviral expression of an antisense SPARC attenuates liver fibrosis." (PMID 21818335, 2011). "In an effort to identify changes in gene expression profile, which could explain the observed protective mechanisms against TAA damage in SPARC−/− mice in an established model of liver fibrosis, microarray analyses were performed." (PMID 23408952, 2013). "Another important event shown in the gene network model is the decrease of CCL19 in SPARC−/− mice, likely involved in the observed reduction in lymphocyte recruitment and process of liver inflammation which normally characterizes liver fibrosis as previously discussed." (PMID 23408952, 2013). "In mouse, SPARC upregulation has only been reported in a schistosomiasis model of liver fibrosis." (PMID 23408952, 2013).
liver fibrosis (continued). "The circulating SPARC concentration is high in NAFLD patients who are likely to progress to the advanced stages of liver fibrosis, and an exercise-induced reduction may lead to a significant improvement in NAFLD, through the suppression of necrosis and inflammation in the liver." (PMID 33898958, 2021). "Two in vivo models of liver fibrosis, based on TAA administration and bile duct ligation, were developed on SPARC wild-type (SPARC+/+) and knock-out (SPARC−/−) mice." (PMID 23408952, 2013). "SPARC is known to be involved in a positive autocrine feedback loop with TGF-β1, a fibrogenic cytokine with a crucial role in liver fibrosis." (PMID 23408952, 2013). "Combined with our own data in liver fibrosis and studies in other organs, we were able to further scrutinize these data to identify a cohort of highly expressed ECM proteins amenable to assay in patient serum samples, including OPN, VIM, SPARC, GPNMB and FN1." (PMID 30559459, 2018).
pancreatic adenocarcinoma (11 papers, 2010 to 2025). "Stromal SPARC expression is observed in almost 40% of pancreatic adenocarcinoma patients who have undergone curative resection, and this expression is an independent prognostic factor." (PMID 32934754, 2020). "Expression of SPARC in human pancreatic adenocarcinoma is often lost due to promoter hypermethylation and this correlates with the switch in TGFβ from a tumor suppressor to tumor promoter." (PMID 22348081, 2012). "The decreased expression of SPARC in ovarian tumors and pancreatic adenocarcinoma is attributed to the aberrant hypermethylation of the SPARC promoter." (PMID 22481923, 2012). "Initially, analysis of pancreatic adenocarcinoma TCGA data confirmed that the methylation levels of BMP3, NPTX2, SPARC, SFRP1 and TFPI2 genes were significantly higher in tumor compared with normal tissue, reinforcing their potential as useful biomarkers." (PMID 37481552, 2023). "We also observed differential methylation of RMRM (reprimo), CLDN5, LHX1, NTPX2, SPARC and ST14, which are already reported as aberrantly methylated genes in pancreatic adenocarcinoma." (PMID 28423671, 2017). "Previously, we demonstrated that in an orthotopic murine model of pancreatic adenocarcinoma, invasion and metastasis was increased in the absence of host SPARC." (PMID 22348081, 2012).
myocardial infarction (10 papers, 2015 to 2024). Gross necrosis of the myocardium, as a result of interruption of the blood supply to the area, as in coronary thrombosis. "This suggests an essential role for SPARC in fibroblast activation, collagen deposition, and extracellular matrix remodeling after myocardial infarction." (PMID 38699584, 2024). "After myocardial infarction, SPARC is expressed by inflammatory cells, suggesting that SPARC produced by infiltrating leukocytes has a role in the inflammatory response and fibrosis in the heart." (PMID 36810547, 2023). "Vice versa, overexpression of SPARC after myocardial infarction showed a cardiac and vascular protective effect." (PMID 33520013, 2021). "Our previous study on SPARC in myocardial infarction suggested a previously unexplored potential inotropic function for SPARC in the heart." (PMID 30933983, 2019). "Previously, our group has shown that SPARC can improve clinical outcome after myocardial infarction by regulating the post-synthetic procollagen processing during fibrosis." (PMID 30933983, 2019). "SPARC has proved to be important for organisation of the scar and maturation of collagen after myocardial infarction; overexpression of SPARC protects against cardiac dilatation." (PMID 25889587, 2015). "Similarly, SPARC inactivation leads to an increase in cardiac rupture and dysfunction after acute myocardial infarction in a mouse model." (PMID 33520013, 2021). "Additionally, overexpression of SPARC by adenoviral delivery in WT animals subjected to myocardial infarction enhanced collagen assembly in these mice and improved cardiac function." (PMID 33147244, 2020). "For example, HSP90 (classified in Immune System) has been found to be involved in the modulation of cardiac ventricular hypertrophy, and SPARC (classified in Hemostasis) has been found to be involved in the improvement of cardiac function after myocardial infarction." (PMID 32582685, 2020). "We have previously shown that SPARC improves cardiac function after myocardial infarction by regulating post-synthetic procollagen processing, however whether SPARC directly affects cardiomyocyte contraction is still unknown." (PMID 30933983, 2019). "We showed how overexpression of SPARC could lead to an improved survival and increased cardiac contraction, as measured by echocardiography, after myocardial infarction in mice." (PMID 30933983, 2019). "Thus, modulation of SPARC production may have potential implications for postinfarction healing, and decorin has a protective role in several cardiac diseases, including atherosclerosis, hypertrophy, and myocardial infarction." (PMID 37533033, 2023).
Osteopenia (10 papers, 2010 to 2025). Osteopenia is a term to define bone density that is not normal but also not as low as osteoporosis. "Recent experiments in mice have shown that deletion of SPARC, one of the NCPs, causes osteopenia due to low bone turnover, which is an apparent defect in both osteoblast and osteoblast activity." (PMID 37892447, 2023). "Moreover, SPARC deficiency leads to osteopenia, which reflects the crucial role that SPARC plays in bone development and structure." (PMID 40299645, 2025). "Moreover, other data of the literature report other ageing-like changes that result from SPARC deficiency, such as reduced bone formation and osteoblast number, osteopenia, diminished levels of collagen, early onset of cataracts, immune alterations, and accelerated degeneration." (PMID 35208200, 2022). "SPARC plays an important regulatory role in bone metabolism: it has been demonstrated that knock-out mice for osteonectin develop osteopenia and have low bone quality." (PMID 36090046, 2022). "SPARC-null mice demonstrate decreases in bone mineral density, develop low-turnover osteopenia at an early age, and exhibit slight decreases in femur length." (PMID 34069164, 2021). "Indeed, deprivation of SPARC causes osteopenia due to decreased numbers of osteoblasts and osteoclasts, suggesting that SPARC may regulate the recruitment or proliferation of osteoblastic precursors, and therefore might represent a potential therapeutically applicable protein." (PMID 31297369, 2019). "SPARC is expressed ubiquitously in mammalian tissues, particularly in adipocytes, and is involved in bone development and turnover and wound healing, especially in corneal tissue; SPARC KO mice have dysregulated collagen and suffer from osteopenia and cataracts." (PMID 41078088, 2025). "SPARC null mice have low-turnover osteopenia, and it was suggested that SPARC may strengthen bone." (PMID 21042566, 2010). "SPARC-null (SPARC−/−) mice display characteristics suggestive of ECM defects, such as early cataract development, progressive osteopenia, lax skin and a curly tail." (PMID 22348081, 2012).